FAP (fibroblast activation protein alpha)
Diseases named in the same sentence as FAP in open-access papers (continued):
Sharing a sentence is not in itself a finding about the gene and the disease.
tumor (continued). "Finally, to evaluate the clinical significance of FAP and DAB2, we further included 90 HCC tumor boundary samples for IHC staining, in which FAP+ CAFs and DAB2+ TAMs enriched around the tumor core." (PMID 39239526, 2024). "Further flow cytometry‐based analysis of co‐cultured GNS cells confirmed that FAP‐CAR‐T cells can kill antigen‐negative tumor cells, but only in the presence of antigen‐positive tumor cells." (PMID 38975278, 2024). "FAP+ mesenchymal cells play an important role in maintaining tumor‐permissive environment in various epithelial cancers, among others by depositing COLI and FN1, which promote tumor invasion." (PMID 38705944, 2024). "However, the clinical use of FAP-CAR T cells is suggested to proceed with caution for occasional poor efficacy and induction of on-target off-tumor toxicity (OTOT), including lethal osteotoxicity and cachexia." (PMID 39086477, 2024). "FAP has pivotal enzymatic and non-enzymatic functions in solid tumors, such as the migration, invasion, adhesion, and proliferation of tumor cells, extracellular matrix remodeling, cancer-associated fibroblast morphology, angiogenesis, and immunosuppression." (PMID 39660049, 2024). "Interestingly, although not significant, we observed a gradual increase in angiopoietin-2, FAP, and VEGF-A levels, as tumor grade increased." (PMID 39511039, 2024). "In biodistribution studies in mice bearing HT-1080 FAP-expressing tumors, comparison with [68Ga]Ga-FAPI-46 showed significantly a higher tumor uptake and tissue-to-blood ratio for [68Ga]Ga-OncoFAP at 1 h p.i., with the parameters at 3 h p.i. becoming similar between the two tracers." (PMID 39765634, 2024). "In recent years, radiolabeled quinoline-based FAP inhibitors (FAPIs) have been developed as a PET radiotracer targeting FAP-expressing cells, inaugurating a new era in molecular imaging, especially for tumor imaging." (PMID 38543082, 2024). "The interaction between FAP+ CAFs and DAB2+ TAMs may be important for the formation of the capsule at the tumor border." (PMID 39239526, 2024). "While the treatment with TGF-β1 neutralizing antibodies could suppress the expression levels of FAP and MMP11 in fibroblasts when co-cultured with UPP1-overexpressing tumor." (PMID 38331898, 2024). "To do this, we distinguished the non-tumor stromal cell components into two categories: those that were negative for KRT which is the entire stroma excluding tumor cells and those that were specifically positive for FAP." (PMID 39035007, 2024). "Furthermore, our above investigations have identified that proliferative tumor cells predominantly reside in close proximity to the triad structure, which comprises SPP1‐expressing macrophages, endothelial cells, and POSTN+FAP+ fibroblasts (middle)." (PMID 39716897, 2024). "FAP expression was not localized to the tumor cells and there was no significant FAP expression in normal background biliary tissue." (PMID 39664608, 2024). "In summary, FAP is expressed in a high proportion (93%) of primary CCA independent of patient clinical or tumor pathology features." (PMID 39664608, 2024). "This specificity is crucial for accurate imaging and subsequent therapeutic targeting, as it ensures that the tracer is selectively accumulating in FAP-expressing tumor cells rather than in non-target tissues." (PMID 39335703, 2024). "In addition, tumor cell-derived conditioned medium (CM) containing abundant extracellular vesicles also increased α-SMA, FAP, IL-1, IL-6, IL-8, CCL5 and CXCL12 expression and enhanced the proliferation, motility and invasion of ADSCs." (PMID 38233863, 2024). "In addition, FAP+ CAFs contribute to ECM desmoplasia, leading to the formation of a dense ECM which limit T cell proximity to PDAC tumor cells." (PMID 39575252, 2024). "FAP exhibited an overall weakly negative correlation with the tumor cell fraction (Spearman ρ = -0.070, p=0.0001)." (PMID 39629134, 2024).
tumor (continued). "According to the authors, this applies particularly, if FAP overexpression is found in the tumor cells rather than the stroma." (PMID 38575990, 2024). "Notably, compared to the tumor with PANC-1 injection alone, the tumor with the co-injection of PANC-1 and CAFs had a stronger positive expression of FAP and α-SMA, indicating that it was CAFs that provided the target for 131I-FAP-2286." (PMID 38360704, 2024). "Although a single anti-FAP NIR-PIT treatment did not result in complete tumor ablation, lung metastases in MMTV-PyVT tumor mice were significantly reduced." (PMID 38275890, 2024). "However, most notably, the combination of FAP-CAR and subsequent Meso-CAR T cells showed the strongest inhibitory effect on tumor growth and tumor burden and had the greatest effect on survival." (PMID 37607999, 2023). "Although our study is not the first work to demonstrate the significant role of FAP in tumor, there is still some innovations." (PMID 37325617, 2023). "The depletion of the FAP + stromal cells or inhibition of the receptor CXCR4 using AMD3100 could lead to rapid accumulation of CD8 + T cells and retard tumor growth." (PMID 38001512, 2023). "Within the CRC cohort, expression of FAP did not correlate with tumor stage, grading or the MSI status." (PMID 37614665, 2023). "In addition, we evaluated the DEGs between PanCK(+) and FAP(+) in EOCC compared to LOCC at tumor invasive margin, tumor center, or adjacent normal areas." (PMID 37964075, 2023). "Notably, FAP-CAR T cells combined with subsequent Meso-CAR T cells significantly increased apoptosis and suppressed proliferation of tumor cells, as evidenced by up-regulated cleaved caspase-3 and down-regulated Ki-67 on tumor cells." (PMID 37607999, 2023). "A study showed that oral FAP-DNA vaccine could induce both CD8+ and CD4+ immune responses, and antitumor immunity was enhanced by combing FAP DNA vaccine with other tumor antigen-specific DNA vaccines." (PMID 37064113, 2023). "Since extracellular matrix organization process plays crucial roles in building the immune-suppressive tumor microenvironment (TME), then we tried to figure out whether FAP was involved in the immune-regulatory process." (PMID 37325617, 2023). "Comparison of FAP labeling between STS entities detected differences in the stained tumor area between STS NOS and UPS (p = 0.0045) and cFS and UPS (p = 0.0105) with the largest stained tumor area in UPS." (PMID 37727209, 2023). "Mechanically, TGF-β1 drives stromal fibroblasts to exhibit tumor-promoting effects through canonical or noncanonical pathways by upregulating the expression of fibroblast activation protein (FAP) and α-smooth muscle actin (α-SMA/ACTA2)." (PMID 37461061, 2023). "A phase 1 clinical trial investigating sibrotuzumab, a humanized monoclonal antibody directed against FAP, in various cancers known to have FAP positivity had no objective tumor responses but it was tolerable." (PMID 37333052, 2023). "In instances where the tumor remains stable, there is an absence of notable variations in serum FAP levels." (PMID 37864148, 2023). "CAFs are the main producers of collagen type I in the TME, but the collagen-positive area did not correlate with the number of tumor-infiltrating FAP+ CAFs." (PMID 38259467, 2023). "Among SUVmax, SUVmean, SUVpeak, metabolic tumour volume (MTV), total lesion FAP expression (TLF), tumour-to-blood background ratio (TBRblood), and tumour-to-muscle background ratio (TBRmuscle), TBRblood was reported to be an independent prognostic factor for short-term outcome." (PMID 37608378, 2023). "FAP promotes the infiltration of MDSCs and tumor-infiltrating macrophages, which may create an immunosuppressive TME that antagonizes anti-tumor immunity." (PMID 38017374, 2023). "Previous studies confirmed that the upregulation of FAPα might enhance the migration and invasion of CRC cells and that its expression increased with the progression of tumor staging." (PMID 36982752, 2023).
tumor (continued). "Immunostaining with an anti-FAP antibody detected the expression of FAP in stromal cells, which are assumed to be CAFs, but not in tumor cells." (PMID 36598731, 2023). "Previous studies have shown that FAP+ CAFs and SPP1+ TAMs contribute to ECM remodeling and coordinate the formation of a prodesmoplastic microenvironment that prevents lymphocytes from infiltrating the tumor core." (PMID 37333982, 2023). "In line with other studies that evaluated FAP expression by IHC, FAP was not correlated to age and gender of the patients nor to the primary site of the tumor." (PMID 37614665, 2023). "However, tumor-related genes (MKI67, CD34) and CAFs (FAP) were downregulated in the Nb-TriTE group compared with the other groups." (PMID 38031188, 2023). "In parallel, DNA damage and tumor cell death induced by beta-particle radiation emitted by 177Lu-FAP-2287 is essentially absent at day 13, further reducing anti-tumor effects." (PMID 37086273, 2023). "Epithelial tumor cells and fibroblasts in benign conditions do not typically express FAP, while expression of FAP on mesenchymal tumor cells was documented by IHC in two human studies." (PMID 37727209, 2023). "They observed an abundant expression of FAP in >70% of tumor samples even without a significant correlation with clinicopathologic factors." (PMID 37111277, 2023). "In addition, the knockdown of FAP resulted in reversed EMT and abolished tumor invasion and pulmonary metastasis induced by TGF-β1-activated CAFs." (PMID 37316886, 2023). "Zhen et al123 developed a nanoparticle-based photoimmunotherapy that enables selective elimination of FAP+ CAFs, which efficaciously retarded tumor growth without endangering other FAP+ populations." (PMID 36708970, 2023). "Nevertheless, throughout literature search, we find that comprehensive analysis of FAP based on big clinical data is still ill-established, and in-depth research of the relationship between FAP expression and tumor immunological profile is still lacking." (PMID 37166418, 2023). "Quinolone-based FAP inhibitors (FAPIs) have been successfully applied to PET imaging in various cancers, providing advantages over conventional 18F-FDG PET/CT in several tumor entities for the initial staging and detection of tumor recurrence and metastases." (PMID 35951090, 2023). "However, depletion of these CAFs by FAP(hF1) UCAR T-cells decreased desmoplasia and enabled subsequently administered Meso UCAR T-cells to infiltrate the tumor." (PMID 37251405, 2023). "Concurrently, a notable reduction in serum FAP level was observed in patients who did not experience tumor recurrence subsequent to successful treatment." (PMID 37864148, 2023). "In conclusion, we identify a unique FAP(+) CAF population that showed WNT signaling upregulation and increased FGF20 levels; while neighbor tumor cells show the upregulation/activation of FGFR2-PI3K/Akt signaling at the tumor invasive margin of EOCC tumors." (PMID 37964075, 2023). "We also observed that the Nb-TriTE induces the specific lysis of FAP+ tumor cells in vitro in a dose-specific and antigen-specific manner, whereas FAP− cells are not affected." (PMID 38031188, 2023). "FAP(+) staining was predominantly detected in non-epithelial cells, with a prevalence at tumor invasive margin." (PMID 37964075, 2023). "In order to evaluate the diagnostic potential and specific tumor accumulation of the αFAP TMs, PET studies were conducted using mice bearing FAP-negative (HT1080) and -positive (HT1080 hFAP) tumors." (PMID 38102692, 2023). "To determine whether FAP overexpression enhances NK cell invasion into these tumor spheroids, we repeated these experiments with NK92 cells and FAP OE NK92 cells." (PMID 38196606, 2023). "In addition, tumor uptake can be effectively blocked by the pre-injection of the reference standard in A549-FAPI tumors, suggesting the specific binding of [18F]3 to FAP in vivo." (PMID 37057133, 2023).
tumor (continued). "There was a weak negative correlation between tumor grade and FAP-stained area (r = −0.3289, p < 0.0162) and a positive correlation with the MI pixel values (r = 0.3691, p = 0.0065) in dogs." (PMID 37727209, 2023). "Furthermore, the mRNA levels of FAP and TNC genes were significantly upregulated in PanCK(-) AOIs at the tumor invasive margin compared to the adjacent normal or tumor center." (PMID 37964075, 2023). "The tumor-targeting properties and the anticancer activity of IL2-7NP2-TNFmut were investigated in vivo in immunocompromised mice bearing SKRC52 cells transduced with human FAP." (PMID 37092450, 2023). "Although our IHC results are promising, the in vitro expression of FAP does not necessarily reflect the in vivo expression of FAP on the surface of tumor cells in STS." (PMID 37727209, 2023). "FAP(hF1) UCAR T-cell pre-treatment with subsequent Meso UCAR T-cell administration exerted maximal tumor growth inhibition and conferred highest survival benefit to tumor-bearing mice compared to the other experimental groups." (PMID 37251405, 2023). "In dogs, we found a non-significant negative correlation between higher tumor grade and FAP expression." (PMID 37727209, 2023). "As FAP has been reported to be involved in the remodeling of the TME, we next examined whether FAP expression was correlated with tumor-infiltrating T lymphocytes in NSCLC tissue." (PMID 35951090, 2023). "Hence, we selected FAP and ITGA5 as biomarkers to detect CAFs and pan-CK as a marker of tumor cells in the following experiment." (PMID 36831470, 2023). "In contrast, we observed significant time-dependent accumulation of CD45.1+GFP+ donor T cells in tumors starting as early as 1-day post-administration of FAP-CAR T cells and the tumor-infiltrating FAP-CAR T cells increased over time at least until 7 days post-administration." (PMID 37607999, 2023). "FAPα expression in tissue correlates with increased angiogenesis and increased capillary density, according to numerous observations in tumor models, but data on fibrosis are currently lacking." (PMID 38136590, 2023). "Elimination of FAP-expressing cells modulates immune suppression of growth, supporting their roles as nonredundant, immune-suppressive components of the tumor microenvironment." (PMID 37046676, 2023). "Taken together, the results indicated that co-injection of anti-BGN HGC27+CAFLCs/sh-control rescued the inhibitory effect of knockdown BGN expression on subcutaneous tumor growth or intraperitoneal tumor dissemination, while co-injection of anti-BGN HGC27+CAFLCs/sh-FAP eliminated the rescued effect." (PMID 36632455, 2023). "In contrast to its high tumor retention in xenograft tissues and in patients, FAP-2286 is not ideally suited for targeting FAP in syngeneic mouse models due to its substantial lower affinity towards murine FAP (KD = 3.8 ± 1.0 nM)." (PMID 37086273, 2023). "The results showed that the area corresponding to the resected tumor showed intense uptake of 68Ga-FAPI-46 (SUVmax, 15.9; SUVmean, 12.8), which was consistent with the results of immunohistochemistry and shows that FAP is strongly expressed in the stroma inside and around the lesions." (PMID 36675506, 2023). "Stromal cellular components of the stromal vascular fraction (SVF) and FAP+CAFs, but not tumor cells, exhibited marked downregulation of Serpine1 mRNA levels, corroborating the stromal source of Serpine1 downregulation." (PMID 37330661, 2023). "While the FAP expression of tumor cells was primarily cytoplasmic in human STS, a more mixed expression in cytoplasm and cell membrane was apparent in canine and feline tumor cells." (PMID 37727209, 2023). "Genetic depletion of FAP allows considerable immunological control of tumors due to the rapid hypoxic necrosis of both cancer and stromal cells via IFN-γ and TNF-α, leading to enhanced infiltration and anti-tumor capacities of T cells." (PMID 37723510, 2023).
tumor (continued). "The direct observation revealed the presence of prominent FAP staining in fibroblasts surrounding the tumor cells, while minimal or absent expression was observed in adjacent normal tissue." (PMID 37864148, 2023). "In the 25 tumors where DSR was absent in the HE staining, only 5 specimens were completely negative for FAP, with the remaining 20 samples presenting only a few positive cells scattered within the tumor area." (PMID 37569808, 2023). "The first hypothesis is that FAP regulates extracellular matrix (ECM) remodeling and reorganization by cleaving substrate peptides or proteins, resulting in promoting tumor cells migration and invasion." (PMID 37166418, 2023). "One significant limitation of the current study is the lack of a preclinical tumor model that reflects the FAP-positive CAF abundance, localization and biology that are observed in human tumors." (PMID 37086273, 2023). "Notably, in the present study, the expression levels of αSMA and FAP, known as CAF markers, were positively correlated with the expression of IL-7R in ESCC tumor nests." (PMID 36672342, 2023). "Since the tumour stroma volume can be bigger than the tumour cells’ volume, stroma-targeted PET imaging can be more sensitive than FDG PET for small peritoneal lesions with sufficient FAP-expressing stroma." (PMID 37608378, 2023). "In regard to MDSCs, FAP+ CAFs releasing CCL2 is recognized by the CCL2 receptor that expressed on circulating MDSCs, leading to the poly-morphonuclear MDSCs infiltration or circulating MDSCs recruitment into the tumor microenvironment." (PMID 37166418, 2023). "Finally, 64Cu-FP-L1, another PET radiotracer, displayed prolonged tumor uptake in models expressing PSMA, FAP, or both." (PMID 37835533, 2023). "It has been reported that FAP-targeted CAR-T cells could induce endogenous T cells infiltration and activation in tumor tissue." (PMID 37046312, 2023). "Once in the tumor stroma, they express α-SMA, FAP, and other CAF-like phenotype markers." (PMID 36899938, 2023). "Indeed, tumor growth inhibition and survival benefit obtained with Meso UCAR T-cell or FAP(hF1) UCAR T-cell treatments alone were significantly lower than with the two combined." (PMID 37251405, 2023). "In our study, we found that SPP1 secreted by APOC1+SPP1+ TAM cells bound to ITGF1 secreted by FAP+ CAFs cells, suggesting that these two subpopulations may promote HCC development by remodeling the tumor microenvironment." (PMID 37333982, 2023). "At 5 h P.I., U87MG tumor was still of a high uptake at 1.81 ± 0.20 %ID/mL, an uptake value only decreased by half when compared with 1.5 h, indicating the stable binding of 99mTc-HYNIC-FAPI-04 to FAP in U87MG tumor." (PMID 36986521, 2023). "Interestingly however, by day 4, and to much greater extent by day 7, after stromal cells and matrix were depleted, FAP-CAR T cells were found escaping from the confines of the stroma and successfully penetrating beyond the tumor borders into tumor nests." (PMID 37607999, 2023). "Regarding NAC response assessment, Backhous and colleagues presented initial results using [68Ga]-labeled FAP inhibitor (FAPI) PET/MRI in 13 women: the mean breast-tumor-to-background ratio was 0.9 for pCR and 2.1 for non-pCR (p = 0.001)." (PMID 37629397, 2023). "Furthermore, it targets FAP-expressing fibroblasts in PDAC299 subcutaneous and orthotopic tumours and induces apoptosis in the subcutaneous tumours upon light exposure." (PMID 37408254, 2023). "Cells that express FAPα have high tumor-initiating capabilities as opposed to epithelial-like cells." (PMID 37759489, 2023). "FAP-transfected cancer cells were used to evaluate the uptake ability of [99mTc]Tc-HYNIC-FAPI because of the lower or non-expression of FAP protein in tumor cells." (PMID 36879039, 2023). "During the post-treatment follow-up, it was observed that the serum FAP level was elevated in cases where clinical manifestations of tumor progression were present, as opposed to those without any clinical symptoms." (PMID 37864148, 2023).